SFTA2 (surfactant associated 2)
Description:
Putative surfactant protein.
Synonyms: SP-G; SFTPG; GSGL541; UNQ541
Tractability: Antibody: UniProt places it where antibodies can reach, with high confidence; UniProt predicts a signal peptide or a membrane-spanning region; its Gene Ontology location is reachable by antibodies, with medium confidence.
Gene: Protein-coding gene on chromosome 6 (30,931,353 to 30,955,636, reverse strand). Ensembl gene ENSG00000196260.
Subcellular location: Secreted; Cytoplasmic vesicle, secretory vesicle; Golgi apparatus
Gene Ontology:
Cellular component: Golgi apparatus; extracellular region; transport vesicle
Genetic constraint (gnomAD): Loss-of-function variants: 3 observed, 6.95 expected, observed/expected ratio (o/e) 0.43, 90% interval 0.2 to 1.11. That is too few expected variants to judge how well the gene tolerates losing a copy. Missense variants: 87 observed, 90.08 expected, observed/expected ratio (o/e) 0.97, 90% interval 0.81 to 1.15. Synonymous variants: 40 observed, 39.9 expected, observed/expected ratio (o/e) 1, 90% interval 0.78 to 1.3.
Homologues: Orthologues: chimpanzee SFTA2 (99% identical), macaque SFTA2 (99% identical), pig SFTA2 (81% identical), dog SFTA2 (69% identical), rabbit SFTA2 (64% identical), mouse Sfta2 (54% identical), rat Sfta2 (51% identical).
Diseases named in the same sentence as SFTA2 in open-access papers:
SFTA2 is named in the same sentence as 19 diseases in open-access papers, as found by Europe PMC text mining. Sharing a sentence is not in itself a finding about the gene and the disease. The quoted sentences say what the papers report.
squamous cell carcinoma (3 papers, 2019 to 2022). A carcinoma arising from squamous epithelial cells. "In addition, the prognostic value of SFTA2 expression differs for patients with lung adenocarcinoma and squamous cell carcinoma." (PMID 36092941, 2022). "SFTA2 was identified as a potential disease-free survival prognostic gene in colon cancer and one of the potential biomarkers for distinguishing between lung adenocarcinoma and squamous cell carcinoma." (PMID 32351322, 2020).
colon cancer (2 papers, 2020 to 2023). "SFTA2 was also identified as a prognostic gene for colon cancer." (PMID 37377935, 2023).
lung adenocarcinoma (2 papers, 2020 to 2022). A carcinoma that arises from the lung and is characterized by the presence of malignant glandular epithelial cells. "We found that SFTA2 serves as a significant tumor suppressor gene and could significantly predict prognosis for patients with lung adenocarcinoma." (PMID 36092941, 2022). "Notably, the expression of lung adenocarcinoma marker genes such as SFTA2 and SFTA3 was widespread and almost completely lost in cancer cells of T790M− tumors." (PMID 36092941, 2022). "In addition, for patients with lung adenocarcinoma from the TCGA database, we found that decreased SFTA2 expression was not markedly associated with PFS (p = 0.059) while significantly predicted poorer OS (p = 0.0066)." (PMID 36092941, 2022).
lung carcinoma (2 papers, 2022 to 2024). "The overall expression of SFTA2 in lung cancer samples was lower in tumor tissues than that in normal lung tissues, and the low expression of SFTA2 was significantly related to the poor progression-free survival of NSCLC patients." (PMID 36092941, 2022). "So far, we have verified that SFTA2 gene could be used as an independent signature to predict the prognosis and TKIs resistance of lung cancer." (PMID 36092941, 2022).
pancreatic ductal adenocarcinoma (2 papers, 2020 to 2022). An infiltrating adenocarcinoma that arises from the epithelial cells of the pancreas. "SFTA2 was also identified as prognostic genes with significantly correlation with the pathological stages of pancreatic ductal adenocarcinoma in an integrated transcriptome meta-analysis." (PMID 36092941, 2022).
breast carcinoma (1 paper, 2025). "Compared with tumors at the primary site, breast cancer tumors that metastasize to the lung show greater expression of genes that are more closely related to lung-specific functions, such as SFTPB and SFTA2." (PMID 40500539, 2025).
colorectal cancer (1 paper, 2026). A primary or metastatic malignant neoplasm that affects the colon or rectum. "This study aimed to investigate the role of surfactant associated 2 (SFTA2) in colorectal cancer (CRC) and its molecular mechanism involving ferroptosis." (PMID 41952768, 2026).
lung disease (1 paper, 2012). "SFTA2 defects may be directly involved in human lung disease." (PMID 22768197, 2012).
cancer (3 papers, 2017 to 2026). A tumor composed of atypical neoplastic, often pleomorphic cells that invade other tissues. "SFTA2 was found to be expressed in cancer cells of CRC patients, associated with key signaling molecules." (PMID 41952768, 2026). "SFTA2 is thus a potentiallyeffective therapeutic strategy for patients with CRC or other cancers." (PMID 41952768, 2026).
tumor (3 papers, 2012 to 2024). "After Cox regression and survival analysis, we demonstrated that higher SFTA2 expression in tumor samples significantly predicts favorable prognosis of NSCLC based on multiple independent cohorts." (PMID 36092941, 2022). "Using RT-qPCR and RNA-seq data from the public database, we found prominently elevated SFTA2 expression in NSCLC tissues compared with normal lung tissues, and the tumor suppressor role of SFTA2 in 82 Chinese patients with NSCLC." (PMID 36092941, 2022). "SFTA2 is expressed in a number of human lung tumors but also tumors of the breast, ovary and cervix as well as tumor-derived cell lines (GeoProfiles)." (PMID 22768197, 2012). "Furthermore, we compared the expression level of SFTA2 in tumor and normal tissues." (PMID 36092941, 2022). "An examination of mRNA levels within the TCGA-GTEx cohort demonstrated a notable increase in KLK10, LAMA3, MET, KRT7, and SFTA2, alongside a decrease in MT1X in tumor samples compared to their normal counterparts." (PMID 38893622, 2024).
adenocarcinoma (2 papers, 2019 to 2025). A common cancer characterized by the presence of malignant glandular cells. "They observed pervasive transcriptional downregulation of adenocarcinoma lineage markers (NAPSA, NKX2-1, SFTA2, and SFTA3), validated orthogonally via multiplex immunohistochemistry." (PMID 41516316, 2025).
SFTA2 also shares sentences with these, for which no sentence is quoted: coeliac disease (1 paper); heart failure (1); hyperthyroidism thyrotoxicosis (1); large cell neuroendocrine carcinoma (1); lung squamous cell carcinoma (1); malignant neoplasm of the thyroid gland (1); non-small cell lung carcinoma (1); schizophrenia (1).